MGMT (O-6-methylguanine-DNA methyltransferase)
Diseases named in the same sentence as MGMT in open-access papers (continued):
Sharing a sentence is not in itself a finding about the gene and the disease.
tumor (continued). "Furthermore, the hypermethylated phenotype of SDHB-related tumours apparently affects the promoter of the MGMT gene encoding the O6-methylguanine-DNA methyltransferase, the repression of which is a biomarker of a good response to alkylating agents such as temozolomide." (PMID 28471419, 2017). "In this study, we found that CagA down regulated the MGMT expression by inducing hypermethylation in its promoter region, suggesting that CagA might induce gastric carcinogenesis by causing hypermethylation of tumor suppressor genes, with the MGMT as a representative." (PMID 26848521, 2016). "Thus, mutations occurring after MGMT silencing may be a minority compared with the previous mutations accumulated during the life of the tumor precursor cells." (PMID 25638164, 2015). "Therefore, tumor MGMT promoter methylation renders cancer cells susceptible to the cell damaging effects of drug regimens utilizing alkylating agents (see also Lessons learned from the DNA methylation biomarker MGMT)." (PMID 25229548, 2014). "In addition, cells with loss of MGMT expression are left unprotected from mutagens and may predispose to additional mutations in the genes involved in the progression of tumours which may lead to advanced stage and poor survival." (PMID 12085181, 2002). "Fourteen-day CBD pretreatment significantly reduced tumor burden compared with both placebo and 3-day CBD groups, accompanied by decreased IDO, PD-L1, MGMT, and Ki67 expression, which are signatures of a less aggressive tumor phenotype." (PMID 41596406, 2026). "Specifically, re-resection should be considered in patients with favourable performance status and tumour characteristics, including methylated MGMT promoter status, and where Gross Total Resection is feasible." (PMID 41530365, 2026). "Aiming at elucidating shared and tumor-distinct features, we analyzed the methylation of MGMT regulatory elements." (PMID 41827844, 2026). "The current clinical use of omics data primarily focuses on genomics for determining the IDH‐ and H3‐wildtype status of the tumor, and on epigenomics, such as assessing MGMT promoter methylation status as a prognostic and predictive biomarker." (PMID 40527506, 2026). "Therapeutic failure is multifactorial, mainly driven by TMZ resistance mediated by DNA repair enzymes (MGMT), and an immunosuppressive tumor microenvironment." (PMID 42076087, 2026). "One possible explanation is that in patients with the most favorable (OFO 1) or least favorable (OFO 4) status, the impact of tumor biology such as MGMT methylation on outcome is more clearly expressed." (PMID 41362480, 2026). "Baseline characteristics were comparable between centers with respect to age, ECOG PS, tumor volume, and MGMT methylation status." (PMID 41575548, 2026). "This study aims to clarify whether different GB subclasses and MGMT promoter methylation status are associated with preferential brain localizations, utilizing a state-of-the-art image post-processing pipeline, as well as an established voxel-wise analysis that focuses on different tumor subregions." (PMID 41597253, 2026). "Patients with SPC (p < 0.001; OR: 0.302; 95% CI: 0.157-0.584) and patients with methylation of the MGMT promoter region (p = 0.005; OR: 0.375; 95% CI: 0.190-0.739) were less likely to receive a tumor-specific therapy in the 30 days prior to death." (PMID 41546074, 2026). "We evaluated the association of the gross tumor volume (GTV)-to-CTV margin with survival, patterns of failure, and its interaction with O6-methylguanine-DNA methyltransferase (MGMT) promoter methylation status." (PMID 42192771, 2026). "Like MGMT, the highest percentage of tumor necrosis was observed in CDKN2A gene amplifications, followed by gene deletions and normal status (p = 0.008)." (PMID 40002588, 2025). "Recent reports highlight the synthetic lethality, a strategy that targets vulnerabilities in tumor cells that lack functional MGMT." (PMID 40895460, 2025).
tumor (continued). "Similarly, the low mutation rate in MGMT may suggest that its expression and promoter methylation status, rather than direct genetic alterations, play a more significant role in treatment response and tumor biology." (PMID 40282990, 2025). "Methylation of the MGMT promoter silences this gene, reducing its repair activity and thereby increasing the tumor’s sensitivity to chemotherapy." (PMID 39796773, 2025). "The main hurdles include toxicity from MGMT inhibitors affecting healthy cells, difficulties delivering these drugs across the blood-brain barrier (especially for brain tumors), and tumor resistance driven by backup DNA repair mechanisms." (PMID 40895460, 2025). "In many cancers, this region becomes hypermethylated, leading to transcriptional silencing of MGMT and making tumor cells more responsive to alkylating agents like TMZ." (PMID 40895460, 2025). "At 6 months of BEV treatment, 19 patients in the MGMT unmethylated group and 14 patients in the methylated group experienced tumor progression, with PFS of 26.9% and 54.8%, respectively (P<0.05)." (PMID 40963873, 2025). "This approach underlies precision trials such as ATTRACT (NCT06512311), which uses patient-derived tumor cultures for ex vivo screening of epigenetic agents to personalize therapy in MGMT-unmethylated GBM." (PMID 41341594, 2025). "As research continues to advance, translating MGMT biology into clinical practice will be critical for developing targeted therapies that improve patient outcomes across a range of tumor types." (PMID 40895460, 2025). "Depletion of USP7 has previously been shown to inhibit tumor progression in various cancers in murine models, and MGMT knockdown in GBM cell-based models reinforces the role of MGMT in TMZ resistance." (PMID 40835840, 2025). "Both monotherapy NPs and Dual-delivery systems, such as temozolomide co-delivered with MGMT-targeting siRNA, have consistently outperformed conventional therapies, significantly reducing tumor burden and extending survival in animal models." (PMID 40944840, 2025). "To compare MGMT wildtype and KO U1242 tumor cell growth in mice brains, we surgically implanted an optimized amount of MGMT WT cells and four different concentrations of MGMT KO cells." (PMID 40336841, 2025). "Tumor cells often develop resistance through O6-methylguanine-DNA methyltransferase (MGMT) expression, DNA repair pathways, and metabolic adaptations that allow survival even with cytotoxic drugs." (PMID 41280918, 2025). "A decrease in MGMT protein levels as well as a raise in cleaved PARP levels was also evident in the tumor lysates from these experiments." (PMID 39997039, 2025). "When the MGMT promoter is methylated, the tumor is more sensitive to chemotherapy, significantly improving patient survival." (PMID 40223032, 2025). "For instance, approaches utilizing cold atmospheric plasma to restore sensitivity to chemotherapy in MGMT-expressing tumor cells have shown promise, indicating a potential avenue for enhancing treatment efficacy." (PMID 40895460, 2025). "In clinical practice, assessing tumor MGMT expression is indirectly accomplished by evaluating the methylation status of the MGMT promoter." (PMID 40336841, 2025). "MGMT (O6-Methylguanine-DNA methyltransferase) is an enzyme that removes the methyl group added to DNA by temozolomide and reduces the damage which would have led to tumour cell death." (PMID 40870498, 2025). "In contrast, patients who underwent chemotherapy, had MGMT promoter methylation, carried IDH1/2 mutations, or received ≥ 50% tumor resection demonstrated better survival outcomes." (PMID 41398783, 2025). "When the MGMT promotor is methylated, the expression of the MGMT enzyme is silenced, reducing the tumor’s ability to repair the DNA damage." (PMID 39992425, 2025). "This silencing correlates with decreased MGMT protein levels and increased tumor sensitivity to alkylating agents, making MGMT promoter methylation a useful prognostic and predictive biomarker." (PMID 40895460, 2025).
tumor (continued). "Mechanistically, the MGMT inhibition by thiolation and nitrosylation is likely to be critical in alkylator-induced tumor cell killing; however, we agree there will be several off-target effects." (PMID 39997039, 2025). "In MGMT, unmethylated tumors, however, leaving residual tumor has a significant impact on patient survival." (PMID 40137412, 2025). "Although ADCmean and rADCmean provide broader tumor characterization, they incorporate heterogeneous components including edema and microscopic necrosis, potentially diluting MGMT-specific signals." (PMID 40958862, 2025). "High MGMT expression in tumor tissues compromises the efficacy of chemotherapy with DNA alkylating agents, such as temozolomide (TMZ)." (PMID 40244270, 2025). "Tumor Treating Fields (TTFields) extend median overall survival (mOS) to 31.6 months in MGMT-methylated patients and 20.9 months overall in supratentorial GBM (EF-14 trial)." (PMID 41007699, 2025). "In a study involving 191 patients, the authors analyzed the predictive value of MGMT status on tumor prognosis in patients with recurrent HGG treated with BEV." (PMID 40963873, 2025). "The effectiveness of TMZ is often enhanced in patients with a methylated MGMT (O6-methylguanine-DNA methyltransferase) promoter, as this gene’s methylation reduces the tumor cells’ ability to repair TMZ-induced DNA damage." (PMID 39796773, 2025). "Targeted editing of the MDK oncogene resulted in ~60% gene editing efficiency, accompanied by a ~70% reduction in MGMT expression and a ~50% inhibition of tumor growth, while sparing healthy brain tissue." (PMID 40725021, 2025). "As expected in Case 10, the MGMT-methylated tumor was sensitive to alkylating agents TMZ and lomustine in vitro." (PMID 41155119, 2025). "Significant differences between non methylated and methylated MGMT GBMs were observed in the total tumor/edema ratio ROI in both DL-models (DeepBraTumIA p < 0.01, Raidionics p < 0.01)." (PMID 41476598, 2025). "High urea levels correlate with tumor markers, as well as Ki67 and MGMT, supporting the rationale of investigating urea-lowering drugs in combination with chemotherapy." (PMID 40775789, 2025). "MGMT (methylguanidine methyltransferase) promoter methylation reduces MGMT protein expression, which leads to increased sensitivity of tumor tissue to chemotherapy with temozolomide and thus improves patient survival." (PMID 39796185, 2025). "Next, we replaced the rMGMT with endogenous MGMT protein by using tumor cell extracts and performing BG-biotin binding assays." (PMID 39997039, 2025). "These included age (P = 0.035), presenting symptoms (P < 0.0001), pre-operative Karnofsky Performance Status (KPS) (P = 0.003), tumor location (P < 0.0001), extent of resection (P = 0.041), MGMT status (P = 0.008), and treatment after surgery (P < 0.0001)." (PMID 41035663, 2025). "Future studies will require confirmation of mRNA levels validated using qPCR methods, protein levels, and signaling mechanisms to expand on these initial findings, especially utilizing TGFB2 and MGMT methylation screens from patient-derived tumor tissues." (PMID 40338274, 2025). "It is therefore possible that the MGMT methylation values for the samples are a combination of various extents of tumor cell contents from the dissection." (PMID 40444102, 2025). "Total-tumor/edema ratio seems to be the single most predictive factor for MGMT-status using multivariate analysis." (PMID 41476598, 2025). "Methylation of the MGMT (O6‐Methylguanine‐DNA‐methyltransferase) promoter reduces MGMT expression, making tumor cells dysregulated in the repair mechanism of drug‐induced DNA damage and more sensitive to chemotherapeutic drugs." (PMID 40264576, 2025). "PI3K/AKT is one of these pathways, which has been shown to promote MGMT expression in multiple tumor types by activating transcriptional regulators such as Sp1." (PMID 41300971, 2025).
tumor (continued). "We delve into the genetic and epigenetic frameworks that shape MGMT expression, illuminating their consequences for genomic stability, tumor dynamics, and resistance to therapy." (PMID 40895460, 2025). "Paraffin‐embedded tumor samples were evaluated by immunohistochemistry (IHC) using an MGMT monoclonal antibody." (PMID 39825572, 2025). "Multivariate analysis revealed TMT (p < 0.001), PNI (p = 0.018), and MCV (p = 0.020) as independent prognostic factors, alongside KPS, extent of tumour resection, postoperative standard chemoradiotherapy, and MGMT status." (PMID 40234099, 2025). "Predictive biomarkers, such as MGMT promoter methylation, specifically help determine whether a patient will benefit from a targeted or cytotoxic therapy; in the case of MGMT, methylation silences the DNA repair enzyme, thus making tumor cells more susceptible to alkylating agents like temozolomide." (PMID 40214448, 2025). "An important factor for her survival was most likely the methylated MGMT promoter status of her tumor that silences the creation of a DNA repair enzyme specifically for alkylation, such as the effects of TMZ." (PMID 39968069, 2025). "These tools can process vast amounts of patient-specific genetic, molecular, and clinical data (e.g., MGMT methylation status) to suggest schemes that optimally suit each tumor’s individual characteristics, even in limited resource settings." (PMID 41007844, 2025). "GSCs expressing MGMT are localized in the tumor’s inner core, where the hypoxia induces fluctuating MGMT expression, contributing to an enhanced protective mechanism against TMZ." (PMID 40358199, 2025). "Testing for MGMT methylation is done through DNA sequencing methods such as pyrosequencing or methylation specific polymerase chain reaction (PCR) on tumor tissue." (PMID 41476598, 2025). "Our study has demonstrated that one of the mechanisms by which tumour cells develop resistance to drugs is through TMZ promoting the transcription of MGMT, which is achieved by activating the ERK pathway." (PMID 39873425, 2025). "The high expression of MGMT in tumor cells reduces their sensitivity to alkylating agents, leading to drug resistance." (PMID 40429865, 2025). "The most impactful of these include a favorable location of the tumor, high extent of resection, better performance status, younger age, and O6-methylguanine-DNA methyltransferase (MGMT) promoter methylation." (PMID 39968069, 2025). "We are currently conducting additional studies to help elucidate the effects of MGMT KO in tumor clonogenicity in soft agar and in vivo." (PMID 40336841, 2025). "By specifically targeting MGMT mRNA, these strategies can achieve tumor-specific effects while minimizing harm to normal tissues." (PMID 40895460, 2025). "Aberrant histone methylation and acetylation, ATRX mutations impacting chromatin stability, and widespread promoter hypermethylation, including MGMT, disrupt the balance between tumor suppressor genes and oncogenic pathways." (PMID 40628732, 2025). "Taken together, most studies have proven that the main resistance of tumour cells to TMZ is the expression level of MGMT." (PMID 39873425, 2025). "Temozolomide (TMZ) is the most common chemotherapy used to treat GBM and is given to patients deemed (via pathological analysis) to possess a methylated O-6-methylguanine-DNA methyltransferase (MGMT) promoter tumor type." (PMID 41463154, 2025). "MGMT repairs cytotoxic lesions caused by TMZ-mediated alkylation of DNA by removing the alkyl group through a suicidal transfer reaction, which irreversibly depletes MGMT protein levels in tumor cells." (PMID 41300971, 2025). "Tumor MGMT promotor was methylated in 31 (39%) of patients in the ipilimumab arm vs 16 (40%) of patients in the temozolomide alone arm." (PMID 40800123, 2025).
tumor (continued). "Current prognostic indicators for GBM widely used include Karnofsky performance scale (KPS) score, tumour resection extent, and O6‐methylguanine‐DNA methyltransferase (MGMT) promoter methylation status." (PMID 40234099, 2025). "In the nude mice bearing T98G and HT29-luc2 xenografts, combinations of hGTX and spermine NONOate with alkylating agents produced a marked reduction in MGMT protein and tumor growth delay and regressions." (PMID 39997039, 2025). "MGMT thus possesses cellular functions related to tumor cell engraftment and anchorage-independent growth beyond guanine methyltransferase repair." (PMID 40336841, 2025). "On the other hand, for GBM patients with a KPS of less than 70 and unmethylated MGMT, RT without TMZ and the best supportive care are offered because expression of the unmethylated MGMT gene by the tumor cell inactivates TMZ." (PMID 39861907, 2025). "This opens the door to combining MGMT inhibition with immune checkpoint blockade to augment anti-tumor responses." (PMID 40895460, 2025). "Liquid biopsies: Circulating tumor DNA (ctDNA) from plasma or cerebrospinal fluid (CSF) can detect epigenetic changes (e.g., MGMT methylation, EZH2 amplification) that predict resistance." (PMID 41234540, 2025). "When the MGMT gene promoter is methylated, it improves the tumor's response to chemotherapy with TMZ." (PMID 40223032, 2025). "Methylation-specific PCR enables the quantification of tumour-specific methylation, such as O6-methylguanine-DNA methyltransferase (MGMT) promoter methylation, a well-established predictor of GBM patient response to alkylating agents like temozolomide (TMZ)." (PMID 40867329, 2025). "Specifically, our study is a retrospective investigation of a modestly sized study cohort confounded by the selection bias of only including patients who received CAPTEM and had tumor samples previously analyzed by MGMT IHC." (PMID 39825572, 2025). "An influence in the proportion of patients with MGMT promoter methylation and tumor response to standard treatment in a sex specific manner have also been identified." (PMID 41346390, 2025). "Alterations in PD-L1 and MGMT expression in tumor tissue paralleled those of β-catenin, suggesting coordinated regulation." (PMID 40809457, 2025). "Several prognostic factors are known to impact the outcomes of h-GBM patients, including MGMT methylation status, age, extent of surgery, performance status, and tumor location." (PMID 40861724, 2025). "TMZ-induced DNA damage is counteracted by the repair enzyme O-6-methylguanine-DNA methyltransferase (MGMT), promoting tumor recurrence." (PMID 40376435, 2025). "Our initial attempts to construct an intracranial tumor model using LN-18 or T98G cells to verify ISP-I’s reduction of MGMT expression in vivo were unsuccessful, due to tumor microenvironment (TME) complexity." (PMID 40809457, 2025). "The highest percentage of tumor necrosis was identified in the case of MGMT > 50%, followed by immunoreactivity of 10–50% and <10%." (PMID 40002588, 2025). "Our results demonstrate, however, that in combination with TMZ the imipridones suppress MGMT expression suggesting potential benefit from combining imipridones with TMZ in CNS as well as other tumor types." (PMID 40145650, 2025). "In the test set, our method achieved promising performance in predicting molecular and histological features, with AUCs of 0.88 for IDH, 0.84 for 1p/19q, 0.85 for MGMT, and 0.94 for tumor grade." (PMID 41293309, 2025). "In contrast, an unmethylated promoter allows for functional MGMT protein production, enabling tumor cells to repair chemotherapeutic damage and leading to inherent treatment resistance and poorer prognosis." (PMID 41295120, 2025).